CYP1A1 (cytochrome P450 family 1 subfamily A member 1)
Diseases named in the same sentence as CYP1A1 in open-access papers (continued):
Sharing a sentence is not in itself a finding about the gene and the disease.
oral cancer (14 papers, 2013 to 2024). "CYP1A1 is a member of the P450 family, the genetic variations of which are associated with the pathogenesis of oral cancer." (PMID 33668218, 2021). "Genotypes from different CYP1A1 polymorphisms were evaluated for their association with different clinical parameters of oral cancer including tumour stage, grade, T status, lymph node involvement and metastasis." (PMID 30803192, 2019). "In conclusion our study suggests a possible association of polymorphisms in CYP1A1 gene with the risk of oral cancer and oral pre cancer." (PMID 30803192, 2019). "In the present study we have observed that among the areca nut/pan masala chewers the risk of oral cancer and precancer been reduced with the TC genotype for T6235C polymorphism in the 3’UTRof CYP1A1 gene." (PMID 30803192, 2019). "We have observed that the haplotypes of CYP1A1 polymorphisms influenced the risk of oral cancer and pre cancer in the population." (PMID 30803192, 2019). "Overall, CYP1A1 rs4646903 polymorphism was closely associated with the increased risk of oral cancer according to the pooled ORs (CC vs TT: OR 1.65, 95% CI 1.33–2.05; CC vs TC+TT: OR 1.77, 95% CI 1.48–2.11; C vs T: OR 1.17, 95% CI 1.07–1.28)." (PMID 26166128, 2015). "Previous studies have demonstrated that CYP1A1 polymorphisms are associated with susceptibility to tobacco-related oral cancers." (PMID 23983642, 2013). "A study conducted in 2015 suggested that the presence of GSTM1 and/or GSTT1 null genotypes, along with variant alleles of CYP1A1, might be the risk alleles for oral cancer in Pashtuns." (PMID 37710250, 2023). "CYP1A1 polymorphisms have been extensively studied with regard to oral cancer risk." (PMID 30803192, 2019). "Our results suggest that genotypes regarding CYP1A1 polymorphisms may modulate the risk of oral cancer and pre-cancer among the areca nut/pan masala consumers." (PMID 30803192, 2019). "For CYP1A1 rs1048943, subgroup analysis by ethnicity indicated that it was related with increased risk of oral cancer in Asians (GG vs AA: OR 1.91, 95% CI 1.20–3.04; GG vs GA+AA: OR 1.76, 95% CI 1.10–2.80; G vs A: OR 1.27, 95% CI 1.07–1.50) but not in whites and other ethnic groups." (PMID 26166128, 2015). "In spite of the absence of any statistical significance, these results strongly supported the previous ones showing that the mutant allele CYP1A1 426Val is related to an increased risk of oral cancer in Caucasians, in the United States, among Asian populations, and in Indians." (PMID 24151610, 2013). "Studies of the association between CYP1A1 polymorphisms and BQ-related oral cancers are scant." (PMID 23983642, 2013). "Materials and Methods: Forty-eight subjects answered the Fagerström, and AUDIT tests and we studied them as likely screening tools for oral cancer and their correlation with the expression of CYP1A1, GSTM1, GSTP1, and GSTT1 genes by the RT-qPCR method." (PMID 35409669, 2022). "In conclusion, our meta-analysis indicates that CYP1A1 rs4646903, rs1048943, and null genotype of GSTM1 polymorphisms are possible risk factors for oral cancer, especially in Asians." (PMID 26166128, 2015). "Our meta-analysis was aimed to evaluate the association of CYP1A1 and glutathione-S-transferase M1 (GSTM1) polymorphisms with oral cancer susceptibility." (PMID 26166128, 2015). "Odds ratios (ORs) with 95% confidence intervals (CIs) were used to evaluate the relationship of CYP1A1 (rs4646903 and rs1048943) and GSTM1 polymorphisms with oral cancer risk." (PMID 26166128, 2015). "Another possibility is that both CYP1A1 and GSTM1 polymorphisms modify oral cancer risk in an ethnic-specific fashion due to different genetic backgrounds." (PMID 26166128, 2015). "The CYP1A1 (426Val/Val) genotype was found three times more frequent than in controls in 3% of oral cancer patients." (PMID 24151610, 2013).
oral cancer (continued). "We have alsodocumented an interaction of genotypes of CYP1A1 polymorphisms with the consumption of areca nut and pan masala as certain genotypes from CYP1A1T6235C, C4887A and A4889G polymorphisms found to alter risk of oral cancer and pre cancer in this group." (PMID 30803192, 2019). "The results demonstrated that CYP1A1 rs4646903 and null genotype of GSTM1 polymorphisms might serve as risk factors for oral cancer." (PMID 26166128, 2015). "Therefore, it is significant to investigate the association of CYP1A1 and GSTM1 polymorphisms with oral cancer risk." (PMID 26166128, 2015). "Nevertheless, it was reported an overrepresentation of the CYP1A1 4889G allele among the nonsmoking Caucasian patients with oral cancer and among the Japanese HNSCC patients." (PMID 24151610, 2013). "In terms of the cytochrome p450 (CYP) metabolism pathway, the polymorphisms of CYP-involved genes (e.g., CYP26B1, CYP1A1, CYP2A6, and CYP2E1) have been found to activate areca nut (AN)-derived nitrosamines, thereby significantly increasing the susceptibility to tobacco-induced oral cancer." (PMID 34422810, 2021). "None of the CYP1A1 polymorphisms were associated with the risk of either oral cancer or pre cancer." (PMID 30803192, 2019). "The involvement of CYP1A1/CYP1A2 and its inhibition by α-naphthoflavone on ANE-induced events suggest that possibly metabolic activation of ANE components is necessary for some of the ANE-induced carcinogenic events and increase the risk of OSF and oral cancer." (PMID 26919242, 2016). "Cigarette smoke has been shown to induce cytochrome P450 (CYP1A1, CYP1B1) and aldo-keto reductase (AKR1C1, AKR1C3, AKR1B10) genes in oral dysplasia and primary oral carcinoma cell lines." (PMID 28467356, 2017). "In overall analysis, CYP1A1 rs4646903 polymorphism was associated with the risk of oral cancer (CC vs TT: OR 1.65, 95% CI 1.33–2.05; CC vs TC+TT: OR 1.77, 95% CI 1.48–2.11; C vs T: OR 1.17, 95% CI 1.07–1.28), whereas rs1048943 showed no obvious association with oral cancer susceptibility." (PMID 26166128, 2015). "Variant genotypes of CYP1A1 might not be considered as risk factors for oral cancer." (PMID 24151610, 2013). "The analysis of the metabolism pathway of PAHs and oral cancer shows a significant gene–gene interaction effect (OR: 2.220 (95% CI: 1.166–4.225), p = 0.0201), and the main effect of each SNP is not significant (p = 0.2008 and 0.8915 for CYP1A1 and GSTM1, respectively)." (PMID 27045371, 2016).
lung adenocarcinoma (11 papers, 2006 to 2024). A carcinoma that arises from the lung and is characterized by the presence of malignant glandular epithelial cells. "We have performed an age-adjusted analysis restricted in males only, which showed a significant association of rs1048943 (CYP1A1) with lung Adenocarcinoma (OR = 2.97, 95% CI = 1.35–6.69, p = 0.007) among smokers." (PMID 34272429, 2021). "We found a nominal association of rs1048943/CYP1A1 with lung Adenocarcinoma (ADC) among smokers in the dominant (GG + GA vs AA: OR = 1.99; 95% CI = 1.10–3.63; p = 0.024) effect model." (PMID 34272429, 2021). "Interestingly, we found a negative effect of age (β = -0.14) on Adenocarcinoma in smokers, which signifies rs1048943 (CYP1A1) to confer risk of developing lung adenocarcinoma in young male smokers." (PMID 34272429, 2021). "CYP1A1 expression has further been reported in 40 out of 107 human lung adenocarcinomas and 21 out of 57 mixed bronchioalveolar carcinomas by immunohistochemistry, whereas the expression of both AhR and CYP1A1 was associated with smoking in lung adenocarcinoma patients." (PMID 19531241, 2009). "CYP1A1 is identified as a CCG in both lung adenocarcinoma (LUAD) and lung squamous cell carcinoma (LUSC), reaffirming our methodology to identify CCGs." (PMID 38642129, 2024). "In CYP1A1, cg18092474 had one of the largest reduction methylation in relation to smoking in lung adenocarcinoma (10.1%), and was one of the sites with largest increased methylation in newborn blood (5.2%)." (PMID 30872662, 2019). "Uppstad and colleagues also showed higher expression of CYP1A1 in cell lines derived from lung adenocarcinoma of female compared to cell lines derived from adenocarcinomas of male patients." (PMID 27008036, 2016). "Associations between CYP1A1 and lung squamous cell carcinoma (SCC) and associations between CYP2E1 and lung adenocarcinoma (AC) were observed, suggesting a specificity of tobacco smoke PAHs for lung SCC and tobacco-specific nitrosamines for lung AC." (PMID 24069431, 2013). "However, the CYP1A1 annotated CpGs hypomethylated in lung adenocarcinoma were also observed to have decreased methylation in adult blood findings." (PMID 30872662, 2019).
ovarian carcinoma (11 papers, 2009 to 2024). A malignant neoplasm originating from the surface ovarian epithelium. "The risk of developing ovarian cancer increased among patients with genetic variants of CYP1A1 Ile462Val, I462V, MspI, and M4." (PMID 38001897, 2023). "Several studies have examined the association between the genotype status of the most common CYP1A1 polymorphisms (Ile462Val, I462V, MspI, M4, and Thr461Asn) and the risk of ovarian cancer development." (PMID 38001897, 2023). "Previous studies have shown that NGFR is linked to WNT/β-catenin signalling and activates ovarian cancer tumour spread, while CYP1A1 was shown to be overexpressed in ovarian cancer clinical samples and to play a carcinogenic role." (PMID 38361045, 2024). "Similar results were obtained with four other ovarian cancer cell lines, demonstrating significant overexpression of CYP1A1 mRNA and protein compared to normal ovary cell lines." (PMID 38001897, 2023). "Few studies have investigated CYP1A1 mRNA and protein expression in ovarian cancer cell lines and clinical specimens." (PMID 38001897, 2023). "In contrast, low expression of CYP1A1 comparable to its expression in normal ovary samples was only detected in 20% of ovarian cancer patient samples." (PMID 38001897, 2023). "We have previously shown that a flaxseed-supplemented diet decreases both the incidence and severity of ovarian cancer in laying hens, also induces CYP1A1 expression in liver." (PMID 33088425, 2020). "Moreover, the CYP1A1 protein was moderately expressed in all examined cases (12 patient samples of ovarian cancer), with its expression confined to the cytoplasm of cells." (PMID 38001897, 2023). "Similarly, moderate-to-high cytoplasmic expression of CYP1A1 was identified in all patient cases of ovarian cancer compared with ovarian benign epithelia and healthy normal tissues." (PMID 38001897, 2023). "Neither the COMT variant nor the CYP1A1 rs4646903 variant were associated with the risk of ovarian cancer on meta-analyses of the published literature and the OCAC data." (PMID 19127255, 2009). "Neither the COMT variant nor the CYP1A1 rs4646903 variant were statistically significantly associated with ovarian cancer risk on meta-analysis (data not shown)." (PMID 19127255, 2009). "5F203 induced enhanced CYP1A1 expression; AhR translocation and reactive species formation (ROS) in IGROV-1 cells and ascites-isolated ovarian cancer cells that were sensitive to 5F203." (PMID 32443455, 2020). "There are no studies exploring the cellular and mechanistic role of CYP1A1 in ovarian cancer." (PMID 38001897, 2023). "In contrast, 5F203 failed to induce CYP1A1 expression, AhR translocation or oxidative stress in 5F203-resistant SKOV-3 cells, or in ovarian cancer ascites cells inherently resistant to this agent." (PMID 32443455, 2020).
atherosclerosis (9 papers, 2014 to 2024). A disease characterized by the build-up of fatty material and calcium deposition in the arterial wall resulting in partial or complete occlusion of the arterial lumen. "According to the physiological and pathological mechanism of CYP1A1, the interaction between CYP1A1 and smoking can cause atherosclerosis." (PMID 25189712, 2014). "In addition to inducing the occurrence of cancers, the polymorphisms of CYP1A1 may also lead to other diseases, such as ulcerative colitis, colorectal adenoma, atherosclerosis, myocardial infarction and so on." (PMID 27384991, 2016). "SRGN and CYP1A1, may be key genes in the endothelial cell response to shear stress in atherosclerosis." (PMID 37491214, 2023). "Studies have shown that CYP1A1 may be involved in the pathogenesis of atherosclerosis and the occurrence of diabetes mellitus and its vascular complications." (PMID 36364780, 2022). "furthermore, this gene can metabolize arachidonic acid into 20-HETE and EETs, which can directly lead to atherosclerosis; However, few studies have excluded the factors related to smoking and independently assessed the relationship between CYP1A1 and coronary heart disease." (PMID 25189712, 2014). "Notably, CYP1A1 and CYP1B1 have been shown to reduce atherosclerosis and vascular dysfunction, respectively." (PMID 37063962, 2023).
diabetes (9 papers, 2012 to 2025). "As noted for WD-fed MR-Intact mice, WD also downregulated genes associated with extracellular matrix in SMC-MR-KO mice (Online Resources 26 and 27) and top upregulated genes also included those implicated in diabetes and obesity, such as Cd36, Txnip, Angptl4, Cyp1a1, and Fabp4." (PMID 36988733, 2023). "In addition, it has been reported that induction of experimental diabetes in rats using streptozotocin (STZ) was associated with elevated CYP1A1 activity levels in diabetic rats compared with the control." (PMID 36418969, 2022). "Regarding diabetes, while hepatic CYP1A1 and CYP2E1 activity and lipid peroxidation (LPO) were enhanced in STZ-induced diabetic rats, insulin treatment attenuated the enzyme activities and LPO levels." (PMID 37428327, 2023). "CYP1A1, HHIP (hedgehog interacting protein), AGTR2, CYP2A6, and PCK1 are involved in growth and development of diabetes mellitus." (PMID 38137330, 2023). "The significance of three-way interaction of exercise, NLE, and diabetes means that the interaction among the two factors (exercise × NLE) is different across the levels of the third factor (diabetes) for AHR, CYP1A1, KYN, IDO1, and MDA." (PMID 37305057, 2023). "The present review aims at providing significant insight into the physiological and pathological role of AhR and its regulated enzymes, such as cytochrome P450 1A1 (CYP1A1) and CYP1B1 in both types of diabetes." (PMID 36418969, 2022). "Concerning diabetes, many studies have focused on CYP2E1 and CYP1A1 enzymes." (PMID 37428327, 2023). "This means that as the body burden of TCDD declined to levels that could not activate AhR, Cyp1a1 gene expression within the liver diminished, leading to diabetes initiation within these mice." (PMID 36418969, 2022).
endometrial cancer (9 papers, 1997 to 2025). Primary or metastatic malignant neoplasm involving the endometrium (mucous membrane that lines the endometrial cavity). "The purpose of this study was to investigate the impact of single nucleotide polymorphisms (SNPs) of the CYP1A1 gene and the gene-environment interaction on the susceptibility to endometrial cancer in Chinese women." (PMID 39384367, 2024). "The CYP polymorphisms that we studied included CYP1A1 I462V and CYP1A1 T461N, as well as CYPIA2 D348N, CYP1A2 I386F, and CYP1A2 C406Y; the CYP1A1 polymorphisms were studied because their incidence is linked to lung, breast, and endometrial cancer." (PMID 32197424, 2020). "However, Xu and Tan studied the impact of single-nucleotide polymorphisms of the CYP1A1 gene and the gene-environment interaction on the susceptibility to endometrial cancer in women (310 endometrial cancer patients and 624 healthy controls)." (PMID 41516250, 2025). "However, few studies were conducted to test the association between SNPs of the CYP1A1 gene and the risk of endometrial cancer in Han Chinese women." (PMID 39384367, 2024). "However, to date, no studies were performed to investigate the impact of interaction between CYP1A1 gene and abdominal obesity on the risk of endometrial cancer." (PMID 39384367, 2024). "In addition, no study was performed to evaluate the impact of synergistic effect between CYP1A1 gene and environmental factors on risk of endometrial cancer in the Chinese population." (PMID 39384367, 2024). "The CYP1A1 gene polymorphism may reduce 2-OH estrogen, increasing the opportunity to exposure to 4-OH estrogen, thus increasing the risk of endometrial cancer." (PMID 39384367, 2024). "However, the results on the relationship between CYP1A1 and the risk of endometrial cancer were inconsistent or even contradictory." (PMID 39384367, 2024). "Therefore, we conducted this study to examine the impact of four SNPs (rs4646421, rs4646903, rs4646422, and rs1048943) of CYP1A1 gene, and the interaction between CYP1A1 gene and environmental factors on the susceptibility of endometrial cancer in Chinese women." (PMID 39384367, 2024). "The biological mechanism of the association between the CYP1A1 gene and the risk of endometrial cancer is not very clear." (PMID 39384367, 2024). "In EA endometrial cancer, the highest scoring bi-clique was the main effect of CYP1A1*2C genotype." (PMID 19287484, 2009).
leukemia (9 papers, 2012 to 2024). A malignant (clonal) hematologic disorder, involving hematopoietic stem cells and characterized by the presence of primitive or atypical myeloid or lymphoid cells in the bone marrow and the blood. "Numerous studies have investigated the relationship between CYP1A1 polymorphisms and leukemia risk, but the results have been inconsistent." (PMID 38485870, 2024). "Therefore, we conducted a meta-analysis of all eligible studies, including ALL in both adults and children, to clarify the associations of CYP1A1 polymorphisms (T3801C and A2455G) with leukemia risk based on genetic models and ethnicity." (PMID 38485870, 2024). "While some studies have suggested an association between the CYP1A1 GG genotype and increased risk of leukemia, the mechanism by which this occurs is not clear." (PMID 39769254, 2024). "In the subgroup analysis according to ethnicity, significant increased leukemia risk was found in the mixed races subgroup but not Asian and Caucasian subgroups, suggesting that CYP1A1 Ile462Val genetic variation may not confer acute leukemia risk among either Asians or Caucasians." (PMID 23056546, 2012).